ENG (endoglin)
Diseases named in the same sentence as ENG in open-access papers (continued):
Sharing a sentence is not in itself a finding about the gene and the disease.
tumor (continued). "All these data reveal that role of ENG in tumor cell behavior is dependent on cell context and must be exploited individually for each cancer." (PMID 33804796, 2021). "One of the noticeable targets of tumor vasculature is CD105 (Endoglin), a transforming growth factor β (TGF-β) coreceptor present on the surface of endothelial cells." (PMID 33802812, 2021). "In conclusion, our understanding of the function of ENG in tumor cells and in the TME has progressed in recent years." (PMID 33804796, 2021). "Compared with endoglin positive normal endothelial cells and human umbilical vein endothelial cells (HUVECs), tumor endothelial cells (TECs) expressing endoglin had a higher resistance to apoptosis, higher cell motility, and stronger proangiogenic traits." (PMID 33809908, 2021). "Some studies have shown that the expression of endoglin in tumor tissues and the serum level of soluble endoglin are positively related to more advanced clinical stages and poor prognosis." (PMID 34252885, 2021). "Endoglin mainly exists in the microvessels of the tumor periphery, whereas TGF-β1 is present only within tumor hepatocytes." (PMID 33809908, 2021). "Tumor endothelial cells have been shown to express endoglin and other angiogenesis-related genes that enhance tube formation and cellular migration." (PMID 33809908, 2021). "Here, we aimed to review and discuss the many roles played by endoglin in different tumor types, as well as the strong evidence provided by pre-clinical and clinical studies that supports the therapeutic targeting of endoglin as a novel clinical strategy." (PMID 33804796, 2021). "ENG (also known as CD105) is a receptor for transforming growth factor β that is expressed at high levels on the cell surface of tumor blood vessels and tumor stromal components." (PMID 34944885, 2021). "There was significant correlation between endoglin expression in the tumor cells and endoglin expression in the endothelial cells." (PMID 33471197, 2021). "With other solid tumor cancers such as prostate, lung (nonsmall cell), rectal, and squamous cell (oral) cancers, the endoglin-labeled microvessel density correlates with tumor progression." (PMID 33809908, 2021). "This study was supported by pre-clinical data showing that resistance to sorafenib was associated with upregulation of ENG and that the addition of TRC105 to sorafenib led to enhanced tumor growth inhibition in preclinical models." (PMID 33804796, 2021). "Based on the endoglin-expressing cells in the tumor microenvironment, i.e., angiogenic endothelial cells, subtypes of fibroblasts, and some malignant epithelial cells, specific endoglin targeting agents have been developed for cancer therapy." (PMID 33946583, 2021). "If the tumor cells express endoglin, shRNA treatment also reduces proliferation and spheroid growth in vitro and tumor growth in vivo." (PMID 33800564, 2021). "In animal models of this tumor type it has been shown that endoglin haploinsufficiency produces less accumulation of CAFs." (PMID 33800564, 2021). "The role of ENG in tumor cells depends on the cell context, in some cases promoting tumor development and progression, and playing an important role in oncogenic signaling, whereas in other cases it has been associated with tumor suppression." (PMID 33804796, 2021). "Endoglin is found to be overexpressed in the tumor neovasculature of brain, lung, breast, stomach and colon." (PMID 34712672, 2021). "Endoglin is involved in angiogenesis, inflammation and cancer-associated fibroblast (CAF) accumulation in the tumor microenvironment (TME)." (PMID 34381735, 2021). "Median overall survival (OS) was compared between patients with low and high levels of endoglin in the tumor cells and the endothelial cells, respectively." (PMID 33471197, 2021). "We expected this approach to boost the anti-tumor activity of endoglin inhibitor by activating T-cell immunity and specifically induce the cytolysis of endothelial cells via T-cell immunity." (PMID 33995664, 2021).
tumor (continued). "In conjunction, these findings demonstrate that ENG expression in several cell types within the TME contributes to tumor progression and metastasis in different cancer models, making it a promising target for microenvironment-directed therapy." (PMID 33804796, 2021). "Some cells derived from HCC produce endoglin in vivo, resulting in the activation of endothelial cells, these cells are referred to as tumor endothelial cells." (PMID 33809908, 2021). "It has been reported that agents that neutralize its antibodies, or a ligand trap targeting endoglin, inhibit BC metastatic spread and tumor angiogenesis in the mice model." (PMID 35010954, 2021). "Future research should aim to explore the precise contribution of ENG expression in specific cell types to tumor progression and metastatic spread using cell-type specific ENG knockout or overexpressing mouse models." (PMID 33804796, 2021). "Survival data were available for 39 patients with newly diagnosed IDH wild-type tumors and information on endoglin levels in tumor cells and for 33 patients with known endoglin expression in the endothelial compartment." (PMID 33471197, 2021). "An evident application of endoglin would therefore be noninvasive, in vivo detection of angiogenesis for diagnosis and prediction of tumor progression." (PMID 33946583, 2021). "The researchers also found that endoglin expression significantly correlated with tumor, node, and metastasis (TNM) staging, differentiation, portal vein invasion, and lymph node metastasis." (PMID 33809908, 2021). "There are two isoforms of CD105: L-endoglin, which is related to tumour development and angiogenesis, and S-endoglin, which has been described to supress tumour invasion and to have an anti-angiogenic effect." (PMID 34639008, 2021). "On the other hand, endoglin is considered a remarkable angiogenic factor whose presence contributes to the development of tumor vasculature." (PMID 34501347, 2021). "Overview of current endoglin-based tumor imaging studies, categorized by imaging modality, disease model, and imaging agent." (PMID 33946583, 2021). "Endoglin is crucial to angiogenesis, and increased endoglin and tumor micro-vessel density is correlated with decreased survival in multiple cancers." (PMID 33819300, 2021). "Carotuximab (TRC105) is a monoclonal antibody to endoglin, an essential angiogenic target highly expressed on proliferating endothelium and both tumor vessels and tumor cells in angiosarcoma." (PMID 34068344, 2021). "SPIONs are commonly used in (preclinical) endoglin-based MR imaging, as they can be readily modified to bind tumor-specific antibodies or to carry drugs, serving as a theragnostic platform." (PMID 33946583, 2021). "Next to its potential for tumor imaging, endoglin was given attention as a selective tumor target for cancer therapy." (PMID 33375670, 2020). "Endoglin-deficient tumors showed increased α-SMA- and NG2-positive cells in the blood vessels, and endoglin-deficient tumor ECs in RIP1-Tag2 mice caused EndMT, which induced Twist expression." (PMID 32467609, 2020). "Although the number of studies describing endoglin on CAFs is still limited, there seems to be a tumor-promoting role for endoglin-expressing CAFs." (PMID 32059544, 2020). "Especially, Endoglin has been exploited to target anti-cancer drugs to the tumor vasculature to treat cancer." (PMID 33287465, 2020). "This work has been extended, with multiple studies showing an important role for endoglin in tumor angiogenesis and strategies for inhibiting tumor angiogenesis by targeting endoglin." (PMID 32059544, 2020). "Its selectively high expression on tumor vessels and its correlation with poor survival in cancer patients led to the exploration of endoglin as a therapeutic target for cancer." (PMID 33375670, 2020).
tumor (continued). "As sEng levels increase, membrane Endoglin staining is predominant in the tumor stroma area and finally disappears when sEng levels are high, which is normally concurrent with high-grade tumoral stages." (PMID 32434528, 2020). "The overexpression of human endoglin is restricted to healing wounds, developing embryos, inflamed tissues, some neoplastic cells and the tumor vascular cells of many solid tumors." (PMID 32316521, 2020). "The combined data of these studies have revealed new insights into the role of endoglin in angiogenesis and its expression and functional role on other cells in the tumor microenvironment." (PMID 33375670, 2020). "Taken together, the collective data on epithelial endoglin expression have revealed that it is tumor type-specific but the role of endoglin in epithelial cancer cell behavior is not yet fully understood." (PMID 32059544, 2020). "In contrast, when sEng levels are increased, the staining of membrane Endoglin is predominantly focused in tumor stroma (very vascularized tissue), and this staining disappears in the tubules." (PMID 32434528, 2020). "In solid malignancies, ENG is almost exclusively expressed in endothelial cells of both peri- and intra-tumoral blood vessels and on tumor stromal components." (PMID 32326402, 2020). "Angiogenesis is essential for tumor growth, so high levels of proangiogenic molecules, such as endoglin, are supposed to be related to greater tumor growth leading to a poor cancer prognosis." (PMID 31897911, 2020). "In contrast to EC, in tumor cells of different origins, in which Endoglin acts as a tumor suppressor, its expression is epigenetically silenced/switched off." (PMID 33287465, 2020). "Researchers have shown that HHEX directly regulates the CD105 gene, which encodes the TGF β co-receptor protein endoglin, and goosecoid, a gene that induces EMT in a variety of tumor cells." (PMID 33425911, 2020). "FAP- and murine endoglin-specific single chain antibody fragments were coupled to the liposomal surface, and the liposomal potentials validated in tumor cells and mice models." (PMID 32316521, 2020). "The pro-angiogenic effects of TGF-β within tumour tissues are mediated via the TGF-β co-receptor CD105 (Endoglin), which is present in abundance within endothelial cells of tumour vasculature." (PMID 32468445, 2020). "Endoglin expression has been reported on tumor-infiltrating Tregs, macrophages, CAFs and cancer (stem) cells in human and mouse samples." (PMID 33375670, 2020). "The role of endoglin in developmental and tumor angiogenesis has been extensively reviewed elsewhere." (PMID 32059544, 2020). "Yet, the tumor ECs express high levels of Endoglin, a BMP9 receptor that is part of the TGFβ receptor complex and an important receptor for endothelial migration and angiogenesis." (PMID 33614496, 2020). "In a neuroblastoma study in immunodeficient NSG mice, it was shown that immunotherapy with the anti-GD2 antibody dinutuximab combined with activated NK cells is suppressed by endoglin-positive cells in the tumor microenvironment." (PMID 33375670, 2020). "The latest, also known as endoglin, is an activated ECs marker, part of the transforming growth factor β receptor complex that plays a key role in tumor-induced angiogenesis." (PMID 33302367, 2020). "Significantly, the expression of ADAMTS1 was upregulated during differentiation of GICs with a similar pattern to endothelial-related CDH5 and ENG genes, supporting the existence of an intrinsic endothelial-like nature within these tumor-promoting cells." (PMID 33396280, 2020). "Given its high and selective expression on tumor blood vessels, endoglin was exploited as a target for tumor imaging." (PMID 33375670, 2020). "In this respect, we prepared bispecific liposomes with 3 main peculiarities, for the simultaneous targeting of FAP and endoglin on the tumor stroma." (PMID 32316521, 2020).
tumor (continued). "The activation of endothelial cells was further confirmed by upregulation of TGF-β1 accessory receptor (CD105), known also as endoglin, because endoglin protein is rarely expressed on the quiescent endothelial cells and is a marker of tumor angiogenesis." (PMID 33271774, 2020). "The results demonstrate highly fluorescence-quenched Bi-FAP/mEnd-IL and their selective binding to FAP and murine endoglin on cultured cells and in vivo in tumor models in mice." (PMID 32316521, 2020). "Next, we conducted IHC to detect the protein levels of ENG in tumor tissue sections from HCC827 xenograft-bearing nude mice." (PMID 32326402, 2020). "We recently reported that CD105 or endoglin is a marker for tumor-initiating cells that functions to maintain self-renewal and chemoresistance in ccRCC." (PMID 31015843, 2019). "The over-expression of endoglin in the endothelial cell was found to promote the tumor growth through the proliferation process, increases the invasion and migration of cancer cells and promotes neovascularization." (PMID 31372176, 2019). "The TGFβ co-receptor endoglin is for example considered to be a vessel marker in tumor biology but is also expressed by malignant cells and has been linked to tumor cell plasticity and worse patient survival in Ewing sarcoma." (PMID 31418125, 2019). "Endoglin has been described as a marker for tumor-related angiogenesis and neovascularization with potential in tumor diagnosis, prognosis, and therapy." (PMID 30991696, 2019). "Functionally endoglin is involved in angiogenesis and intratumoral endoglin level is an important marker of tumor angiogenesis and neovascularization process." (PMID 31500214, 2019). "Endoglin (ENG) is known as a critical factor for tumor invasion by enhancing formation of invadopodia, extracellular proteolysis, chemotaxis, and migration." (PMID 30467308, 2018). "On the other hand, increased endoglin expression in tumour cells correlates with tumour suppression, whereas downregulation of endoglin leads to tumour progression, allowing migration, invasion and malignancy." (PMID 30563158, 2018). "The main mechanism that stimulates endoglin production in the HCC is the hypoxia of the tumour environment." (PMID 30563158, 2018). "Some report that tissue expression in ECs of tumour tissue, as well as soluble endoglin (Sol-ENG) serum levels, positively correlate with more advanced clinical stage and/or poor prognosis." (PMID 30563158, 2018). "Depending on the type of a tumour and endoglin producing cells (vascular ECs vs. tumour cells), this protein can serve dual roles (growth/tumour progression or inhibition/tumour suppression) in carcinogenesis." (PMID 30563158, 2018). "Correlation of our in vitro finding with TCGA data suggests an in vivo association between NF1 status and tumor production of CHI3L1 and ENG, supporting an association between NF1 and mesenchymal identity in human GBM samples." (PMID 29643433, 2018). "Our group has conducted studies of tumor microenvironment polarization using combination of endoglin-based DNA vaccine (ENG vaccine) with interleukin 12 (IL-12)." (PMID 29320562, 2018). "The change of blood vessel phenotype involves the appearance of new endothelial tumour markers, e.g., VEGFRs, and/or endoglin." (PMID 30563158, 2018). "Activated T lymphocytes were specifically targeted against endoglin expressing endothelial and tumor cells." (PMID 29320562, 2018). "Here, we demonstrated that combination of endoglin-based DNA vaccine with interleukin 12 repolarizes TAMs from tumor growth-promoting M2-like phenotype to tumor growth-inhibiting M1-like phenotype." (PMID 29320562, 2018). "In HCC, there is a tight relation between overproduction of endoglin by proliferation tumour ECs (TECs) and creation of sinusoid-like, branching, and small endothelial sprouts." (PMID 30563158, 2018).
tumor (continued). "Since the first study published in 1995 found the upregulation of ENG protein expression in tumor vascular endothelial cells, more and more studies have explored the role of ENG on the occurrence and development of tumors." (PMID 29484142, 2018). "In summary, this is the first meta-analysis with strong evidence that increased ENG protein expression in tumor microvessel is correlated to the poor OS, DFS, and CSS." (PMID 29484142, 2018). "CD105 (Endoglin) is one of the tumor-related angiogenesis factors that is upregulated in tumor tissues and neovascularization." (PMID 29276515, 2017). "Proinflammatory cytokines (IFNγ, MCP1, MIP1α, and TNFα) and myeloid differentiation factor (Endoglin) were increased in myeloid cells from p65 KO tumor, which demonstrated an influence on CD8+T cell proliferation." (PMID 29062041, 2017). "ENG expression is upregulated in endothelial cells during wound healing and tumor vascularization, and in inflammatory tissues and developing embryos, indicating that ENG is an endothelial proliferation marker." (PMID 29098173, 2017). "Prostate sections were stained with antibodies specific for CD105 (endoglin), which is currently considered a good marker for proliferating endothelial cells and newly forming tumor vessels." (PMID 28567040, 2017). "Endoglin is considered a marker for evaluating microvessel density in tumors, and has also been reported as a target of tumor neovasculature for cancer therapy." (PMID 27294959, 2016). "Endoglin is highly expressed on proliferating endothelium including that of a range of human tumours." (PMID 26620208, 2016). "Surprisingly, a reduced dosage of the endoglin gene gives rise to an increase in metastatic spread due to adoption of a mesenchymal phenotype by endothelial cells, which in turn leads to enhanced tumor cell intravasation." (PMID 27741515, 2016). "TRC105, a novel chimeric IgG1 anti-CD105/endoglin monoclonal antibody with high avidity, induces antibody-dependent cellular cytotoxicity and apoptosis in human umbilical vein endothelial cells and CD105+ tumor cells." (PMID 27891093, 2016). "Targeting endoglin over-expressed in tumor neovasculature has been used for therapeutic purposes with anti-endoglin antibodies, endoglin-targeted radioimmunotherapy, and anti-endoglin antibody–containing ITs." (PMID 27294959, 2016). "Endoglin (CD105) has been suggested to be the most suitable marker available to quantify tumor angiogenesis." (PMID 27102733, 2016). "Dual targeting of ALK1 and endoglin resulted in further inhibition of tumor growth, indicating that the most effective means to achieve repression of TGF-β signaling in endothelial cells is by blocking both receptors." (PMID 27741515, 2016). "In PlGF-blocked tumours, fewer capillaries, as shown by endoglin staining, were tortuous (aPlGF: p < 0.05 and PlGFKO: p < 0.01)." (PMID 26753564, 2016). "Renal CSCs isolated from nephrectomy specimens express CD105/endoglin, allowing valuable therapeutic target for the tumor vasculature." (PMID 27891093, 2016). "Targeting endoglin with immunotoxins containing type 2 ribosome-inactivating proteins has proved an effective tool to reduce blood supply to B16 mice tumor xenografts." (PMID 27294959, 2016). "While targeting of ALK1 gives rise to suppression of key parameters, including tumor volume, vessel density and metastatic dissemination, suppression of endoglin enhances seeding of metastases." (PMID 27741515, 2016). "Conversely, in our comparative studies, genetic targeting of endoglin (gene name Eng), either globally or in an endothelial cell-restricted manner, only transiently impacts on tumor growth and angiogenesis." (PMID 27741515, 2016). "Recently, endoglin has been identified as a key regulator of tumor cells proliferation, migration, and invasion." (PMID 26089870, 2015). "Nigrin b and ebulin l have also been used to construct immunotoxins containing antihuman CD105 (endoglin) to target tumour neovasculature." (PMID 25647575, 2015).